SHISAL2A (shisa like 2A)
Synonyms: FAM159A; MGC52498; PRO7171; WWLS2783
Tractability: Antibody: UniProt predicts a signal peptide or a membrane-spanning region.
Gene: Protein-coding gene on chromosome 1 (52,633,168 to 52,669,683, forward strand). Ensembl gene ENSG00000182183.
Subcellular location: Membrane
Gene Ontology:
Molecular function: protein binding
Cellular component: membrane
Genetic constraint (gnomAD): Loss-of-function variants: 18 observed, 12.97 expected, observed/expected ratio (o/e) 1.39, 90% interval 0.95 to 1.88. The upper end of that interval is the gene's LOEUF score, 1.88, which puts it in group 6 of 6, group 1 being the genes least tolerant of losing a copy. Missense variants: 261 observed, 258.9 expected, observed/expected ratio (o/e) 1.01, 90% interval 0.91 to 1.12. Synonymous variants: 94 observed, 104.05 expected, observed/expected ratio (o/e) 0.9, 90% interval 0.76 to 1.07.
Homologues: Orthologues: chimpanzee SHISAL2A (99% identical), macaque SHISAL2A (95% identical), pig SHISAL2A (78% identical), rat Shisal2a (77% identical), dog SHISAL2A (76% identical), mouse Shisal2a (75% identical), rabbit SHISAL2A (55% identical), tropical clawed frog shisal2a (48% identical), zebrafish SHISAL2A (38% identical). Paralogues in human: SHISAL2B (37% identical), SHISA4 (19% identical), SHISA2 (17% identical), SHISAL1 (16% identical), SHISA3 (16% identical).
Diseases named in the same sentence as SHISAL2A in open-access papers:
SHISAL2A is named in the same sentence as 2 diseases in open-access papers, as found by Europe PMC text mining. Sharing a sentence is not in itself a finding about the gene and the disease.
SHISAL2A shares sentences with these, for which no sentence is quoted: breast carcinoma (1 paper); Sensory neuropathy (1).